GPER1 (G protein-coupled estrogen receptor 1)
Diseases named in the same sentence as GPER1 in open-access papers (continued):
Sharing a sentence is not in itself a finding about the gene and the disease.
gallstones (6 papers, 2020 to 2025). Solid crystalline precipitates in the biliary tract, usually formed in the gallbladder, resulting in the condition of cholelithiasis. "As found by a powerful genetic quantitative trait locus (QTL) analysis, Gper1 is a new gallstone gene, Lith18, on chromosome 5 in mice." (PMID 33281743, 2020). "More recently, exciting evidence shows that a novel, potent GPER1-selective antagonist, CIMBA, reduces the prevalence of E2-induced gallstones in a dose-dependent manner by impeding the GPER1 signaling pathway in female wild-type mice." (PMID 33281743, 2020). "This review discusses the complex signaling pathways of three estrogen receptors, highlights the development of GPER1-specific ligands, and summarizes the latest advances in the role of GPER1 in the pathogenesis of gallstone formation." (PMID 33281743, 2020). "This indicates that GPER1 produces a synergistic lithogenic action with ESR1 to enhance E2-induced gallstone formation." (PMID 33281743, 2020). "Indeed, G-1 impairs gallbladder emptying through the GPER1 pathway in mice, leading to sluggish gallbladder motility and accelerating the development of biliary sludge in the early stage of gallstone formation." (PMID 33281743, 2020). "Overall, the prevention of lithogensis via a GPER1 antagonist represents a novel treatment option for high-risk populations and may prove to be an adjunct therapy to nonsurgical gallstone treatments." (PMID 33281743, 2020). "Overall, these studies have established a novel concept that GPER1 is involved in E2-dependent lithogenic actions, working independently of ESR1, as both GPER1 and ESR1 can promote the formation of E2-induced gallstones through different pathways." (PMID 33281743, 2020). "In this circumstance, previous evidence has shown that inhibition of ESR1 or GPER1 alone is not sufficient to completely prevent gallstone formation." (PMID 33281743, 2020).
inflammatory breast carcinoma (6 papers, 2013 to 2024). An advanced, invasive breast adenocarcinoma characterized by the presence of distinct changes in the overlying skin. "GPER-1 overexpression has been observed in invasive ductal carcinomas of the breast when compared to adjacent healthy tissue and in inflammatory breast cancer, a more aggressive form of this neoplasia." (PMID 33117280, 2020). "Coexpression of GPER-1 and ER was found in almost 24% patients with inflammatory breast cancer, while 19% only express ER and 46% only express GPER-1." (PMID 27314054, 2016).
ovarian tumors (6 papers, 2012 to 2023). "This study was undertaken to put more clearance in the role of GPER-1 in ovarian tumor biology." (PMID 23849542, 2013). "Moreover, GPER-1 expression decreased from benign to malignant ovarian tumours." (PMID 23849542, 2013).
preeclampsia (6 papers, 2015 to 2025). Preeclampsia is a hypertensive disorder of pregnancy that is characterized by new-onset hypertension with proteinuria presenting after 20 weeks of gestation, and depending on mild or severe forms may initially present with severe headache, visual disturbances, and hyperreflexia. "Moreover, the level of GPER1 in placentas from preeclampsia reduced by about 50%, a reduction that can partially be associated with estrogen treatment in trophoblast culture, which correlates with elevated apoptosis and minor cellular proliferation in the placenta from preeclampsia." (PMID 34867473, 2021).
Alzheimer disease (5 papers, 2021 to 2025). A progressive, neurodegenerative disease characterized by loss of function and death of nerve cells in several areas of the brain leading to loss of cognitive function such as memory and language. "Neurodegenerative disorders, particularly Alzheimer’s disease (AD), further substantiate ER-β and GPER1’s neuroprotective roles." (PMID 40995073, 2025). "Again, most of the data refer to GPER1-mediated effects, particularly with respect to mood disorders, Alzheimer’s disease, and traumatic brain injury, which have been studied in rodent models." (PMID 36835454, 2023).
endometrial tumor (5 papers, 2013 to 2022). "Taken together, these results suggested that AMF might affect endometrial tumor growth via GPER-1." (PMID 30836961, 2019).
heart failure (5 papers, 2012 to 2022). Inability of the heart to pump blood at an adequate rate to meet tissue metabolic requirements. "The GPER1 agonist G1 reduced the risk of isoproterenol-induced heart failure in female mice." (PMID 36060947, 2022). "ERα, ERβ, and GPER1 protect against I/R injury and heart failure." (PMID 36060947, 2022).
Hyperglycemia (5 papers, 2019 to 2024). An increased concentration of glucose in the blood. "Beyond the observed dysregulation of adipogenesis, others reported that male GPER1 KO mice developed hyperinsulinemia and hyperglycemia by 18 months of age and female GPER1 KO mice developed impaired glucose tolerance within 6 months of age." (PMID 31242463, 2019).
liver cancer (5 papers, 2016 to 2025). An epithelial or non-epithelial malignant neoplasm that arises from the liver. "Inhibitors of G-protein-coupled estrogen receptor (GPER1) that have been characterized could be used to treat or prevent liver cancer." (PMID 34671598, 2021).
mantle cell lymphoma (5 papers, 2020 to 2024). Mantle cell lymphoma is a rare form of malignant non-Hodgkin lymphoma affecting B lymphocytes in the lymph nodes in a region called the ``mantle zone''. "Furthermore, GPER1 is found in the majority of mantle cell lymphoma cases, suggesting that therapies targeting GPER1 could benefit these patients." (PMID 39684286, 2024).
memory impairment (5 papers, 2019 to 2024). "Therefore, GPER1 activity may be a new target in the treatment of SZ and other symptoms, such as learning and memory impairment." (PMID 33324181, 2020).
osteoarthritis (5 papers, 2020 to 2025). A noninflammatory degenerative joint disease occurring chiefly in older persons, characterized by degeneration of the articular cartilage, hypertrophy of bone at the margins and changes in the synovial membrane. "In a model of osteoarthritis, which is a progressive inflammation joint disease, the role of GPER1 in protecting chondrocytes against mitophagy was via PI3K signaling." (PMID 34239558, 2021).
bladder cancer (4 papers, 2015 to 2025). "In addition to nuclear ERs, G protein-coupled estrogen receptor 1 (also known as GPR30) isolated as a membrane ER was found to inhibit the growth of bladder cancer cells." (PMID 40486871, 2025).
female reproductive cancer (4 papers, 2015 to 2024). "Moreover, immunohistochemical studies have shown a positive association between the expression of GPER1 and the progression of female reproductive cancer." (PMID 34631510, 2021).
invasive ductal carcinoma (4 papers, 2015 to 2020). "Equally, GPER1 gene expression was observed to be lower in infiltrating ductal carcinoma than in nontumor mammary tissues and also lower in the polycystic ovary syndrome group than in normal group." (PMID 25861267, 2015).
liver fibrosis (4 papers, 2021 to 2025). "Our data indicated that AMPK activation mediated by GPER1 reduces lipid accumulation by enhancing lipogenesis and reducing lipolysis and ameliorates liver fibrosis by inhibiting the transcription of fibrosis-related factors." (PMID 38246352, 2024). "In the meanwhile, the role of the GPER1/autophagy pathway in SSd-induced LF alleviation was further validated, since autophagy activator RAPA and GPER1 antagonist G15 significantly impeded the promotive effects of SSd on liver fibrosis regression." (PMID 36499429, 2022). "The current data demonstrate that SSd treatment contributes to alleviate liver fibrosis through regulating GPER1/autophagy pathway." (PMID 34714484, 2021). "Collectively, the current data demonstrate that SSd alleviated liver fibrosis through regulating GPER1/autophagy pathway." (PMID 34714484, 2021). "In summary, the current data demonstrate that SSd alleviated liver fibrosis through regulating GPER1/autophagy pathway." (PMID 34714484, 2021). "Our findings highlight that SSd alleviates hepatic fibrosis by regulating GPER1/autophagy pathway." (PMID 34714484, 2021). "Then we investigated whether SSd treatment alleviated liver fibrosis through regulating GPER1/autophagy pathway." (PMID 34714484, 2021). "The current data verify the role of SSd in repressing HSCs activation and liver fibrosis by regulating GPER1/autophagy pathway, and might be used as potential agent to treat liver fibrosis." (PMID 34714484, 2021). "ERβ activation has also been implicated in reducing hepatic fibrosis in vivo in a carbon tetrachloride rat model of cirrhosis; treatment with a selective ERβ antagonist (and not selective ERα or GPER1 antagonists) abolished the beneficial effect of E2 on liver fibrosis scores." (PMID 40522859, 2025). "Finally, we investigated whether SSd alleviated liver fibrosis through regulating GPER1/autophagy pathway." (PMID 34714484, 2021). "They observed that SSd could effectively alleviate fibrosis and down-regulate autophagy by recovering the expression of GPER1 in TGFβ1-treated LX2 cells and carbon tetrachloride (CCl4)-induced hepatic fibrosis mice." (PMID 36499429, 2022).
myocardial infarct (4 papers, 2015 to 2024). "We regard the nearly 6-fold GPER1 mRNA upregulation as cardioprotective, given that its activation via G-1 (a well-known agonist for GPER1 receptor) reduced myocardial infarction and fibrosis." (PMID 39285385, 2024). "In isolated rat hearts subjected to I/R, GPER1 activation was shown to improve functional recovery and reduce myocardial infarct size." (PMID 33193095, 2020). "Finally, our findings raise the intriguing possibility to therapeutically target Gper1 in a clinical setting in order to protect against acute myocardial infarction." (PMID 26356837, 2015).
neuroblastoma (4 papers, 2019 to 2023). Neuroblastoma (NB) is the most common solid, extracranial childhood tumor. "However, there is some evidence for crosstalk between these receptors including GPER1 activation rapidly downregulating μ-opioid receptors in the arcuate nucleus as well as eliciting phosphorylation of μ-opioid receptors in human neuroblastoma SH-SY5Y cells." (PMID 34391470, 2021).
squamous cell carcinoma (4 papers, 2012 to 2023). A carcinoma arising from squamous epithelial cells. "The tissue microarray was analyzed for the presence of GPER1 revealing that, among other findings, in hyperplasia an accumulation of GPER1 was observed in the epithelial layer, while in squamous cell carcinoma samples an accumulation was observed in the stroma with infiltrating tumor cells." (PMID 37762008, 2023).
uveal melanoma (4 papers, 2023 to 2024). A melanoma derived from melanocytes of the uveal tract. "In vitro treatment of uveal melanoma cell lines with GPER1 agonist induced mitotic arrest and apoptosis of tumor cells." (PMID 39252786, 2024).
anxiety disorder (3 papers, 2022 to 2024). A category of psychiatric disorders which are characterized by anxious feelings or fear often accompanied by physical symptoms associated with anxiety. "However, non-classical signaling via transmembrane receptors, such as GPER1 also appears to play a significant role in the pathophysiology of anxiety disorders in both males and females." (PMID 36159923, 2022). "Therefore, in humans, GPER1 protein could be a possible candidate for a peripheral biomarker in anxiety disorders." (PMID 36159923, 2022). "SSHs in the pathophysiology of anxiety disorders appear to include signaling in the HIP, AMY, PFC, or HPA/HPG axes via ERβ (or GPER1 concerning the antidepressant-like effects in female rats) in females and AR signaling in males." (PMID 36159923, 2022). "The negative correlation of classical effects of E2 was contrasted with the positive correlation of non-classical effects of E2 via GPER1 in anxiety disorders in both sexes." (PMID 36159923, 2022). "Additionally, Estradiol valerate was also identified as a potential lifespan-extending drug for both MDD with and without anxiety disorder, by targeting the G protein-coupled estrogen receptor 1 (GPER1) gene." (PMID 38926475, 2024).
autoimmune disease (3 papers, 2021 to 2025). A disorder resulting from loss of function or tissue destruction of an organ or multiple organs, arising from humoral or cellular immune responses of the individual to their own tissue constituents. "The estrogens/GPER1 signaling plays important roles in various physiological contexts and has been found to mediate sex differences in the incidence and severity of cardiovascular and autoimmune diseases." (PMID 39582864, 2024).
esophageal cancer (3 papers, 2021 to 2023). A primary or metastatic malignant neoplasm involving the esophagus. "The interaction among the GPER1, ER, and ER variants in esophageal cancer requires further study to explore." (PMID 37762356, 2023). "This study demonstrated that different histological subtypes of esophageal cancer had different GPER1 expression patterns." (PMID 37762356, 2023). "Barrett’s esophagus is one of the key risk factors and precancerous lesions of EAC, which prompted us to suspect the presence of various expression characteristics of GPER1 in different histological types of esophageal cancer." (PMID 37762356, 2023). "Considering that the various subtypes of esophageal cancer have quite different features and epidemiology, we explored the expression levels of GPER1 RNA in different pathologic alterations of the esophagus." (PMID 37762356, 2023). "In the present study, the mRNA levels of GPER1 in esophageal carcinoma were collected from GEPIA and Oncomine databases for meta-analyses." (PMID 37762356, 2023). "Analysis of the RNA levels from the databases showed a decreased expression of GPER1 in overall esophageal carcinoma, and low expression levels of GPER1 were found to be associated with low survival of tumor patients." (PMID 37762356, 2023). "The RNA-level analysis of various ERs from the database indicates that estrogen might play a role in the incidence bias of esophageal cancer mainly through GPER1." (PMID 37762356, 2023). "However, the expression levels of GPER1 RNA were reduced in the overall esophageal cancer tissues compared with the normal esophageal tissues." (PMID 37762356, 2023). "Analysis of the data showed that GPER1 mRNA levels were lower in the esophageal carcinoma tissues than the normal esophageal tissues (p < 0.05), and samples with low GPER1 (n = 91) RNA levels showed a lower survival rate than those with high levels (n = 91) of GPER1 RNA (p < 0.01)." (PMID 37762356, 2023). "The results of this study indicate that the expression levels of GPER1 are higher in EAC than in ESCC, which might be correlated with the dimorphic estrogen signaling pathway in different types of esophageal carcinoma." (PMID 37762356, 2023). "The G protein-coupled estrogen receptor 1 (GPER1) is involved in several sex-related cancers; however, its expression level in esophageal carcinoma has been poorly investigated and its role is not precisely defined, depending on histological types." (PMID 37762356, 2023). "The results showed that EAC expressed higher levels of GPER1, while ESCC showed relatively lower levels of GPER1 compared with normal esophageal samples, which indicated that the GPER1 protein exhibited a different expression pattern in the subtype of esophageal cancer." (PMID 37762356, 2023).
glioma (3 papers, 2018 to 2023). A benign or malignant brain and spinal cord tumor that arises from glial cells (astrocytes, oligodendrocytes, ependymal cells). "A high GPER1 level associated with a high expression of key genes involved in angiogenesis such as PDGFRB, which enhanced glioma cell migration and was proposed together with EGFR as a target for therapeutic agents." (PMID 36077653, 2022). "In IDHmut tumors, female-specific genes positively associated to GPER1 were mainly regulated by upstream factors such as HMG1, which mediates GBM regression and promotes angiogenesis, and ERRα, with expression that increases with glioma grade." (PMID 36077653, 2022). "No data are currently available on the involvement of GPER1 in low-grade gliomas." (PMID 36077653, 2022).
Infertility (3 papers, 2020 to 2024). "Some of these genes were also associated with male fertility or infertility in mammals (e.g., CEP78, GPER1)." (PMID 38540441, 2024). "Some of the genes presented, such as CCSER1, GNAQ, NCOA2, SNRK, and TSPO, have been previously associated with fertility traits in livestock species or related to infertility in human patients (CEP78 and GPER1)." (PMID 38540441, 2024).
lymphoma (3 papers, 2020 to 2025). A malignant (clonal) proliferation of B- lymphocytes or T- lymphocytes which involves the lymph nodes, bone marrow and/or extranodal sites. "Although CCR3, CCR6, CCR8, PITPNM3, and GPER1 encode receptors of CCL18, only CCR6 was expressed in the lymphoma cells." (PMID 39894788, 2025).
mood disorder (3 papers, 2020 to 2024). A cognitive disorder a disturbance in which the person's mood is hypothesized to be the main underlying feature. "Recently, the role of GPER1 in the regulation of mood disorders has been described." (PMID 33324181, 2020).
non-small cell lung carcinoma (3 papers, 2012 to 2025). A group of at least three distinct histological types of lung cancer, including non-small cell squamous cell carcinoma, adenocarcinoma, and large cell carcinoma. "In human non-small-cell lung cancer cell lines, the expression of cytoplasmic GPER1 was high and treatment of non-small-cell lung cancer cell lines with GPER1 antagonists impaired tumor growth." (PMID 39252786, 2024). "G protein-coupled estrogen receptor 1 (GPER1), which reduces H2O2 cytotoxicity and decreases sensitivity to the ferroptosis inducer RSL3, impairs lipid peroxidation in non-small cell lung cancer." (PMID 39935430, 2025).
Sepsis (3 papers, 2023 to 2025). Sepsis is defined as life-threatening organ dysfunction caused by a dysregulated host response to infection. "Additionally, GPER-1 activation in males mirrors these benefits, improving cardiac function and survival rates, suggesting GPER-1 as a potential therapeutic target for sepsis treatment." (PMID 40458798, 2025). "In a prospective ICU study, sepsis survivors showed significantly higher GPER-1 concentrations and more favorable clinical parameters compared to nonsurvivors, including higher platelet counts, CRP levels, SOFA, and APACHE II scores—all positively correlated with GPER-1 levels." (PMID 40558557, 2025). "While not the sole explanation, the GPER-1/PPARδ axis offers a compelling rationale for sex differences in sepsis outcomes, including reduced mortality, vasopressor requirements, and faster hemodynamic recovery." (PMID 40558557, 2025).
Uterine leiomyoma (3 papers, 2019 to 2021). The presence of a leiomyoma of the uterus. "Compared with normal uterine tissues, the expression of GPER1 in uterine leiomyoma is higher and increases cell migration, which may be one reason for its high expression in AAAs." (PMID 33362847, 2020).